TRMT6 (tRNA methyltransferase 6 non-catalytic subunit)
Description:
Substrate-binding subunit of tRNA (adenine-N(1)-)- methyltransferase, which catalyzes the formation of N(1)-methyladenine at position 58 (m1A58) in initiator methionyl-tRNA. Together with the TRMT61A catalytic subunit, part of a mRNA N(1)- methyltransferase complex that mediates methylation of adenosine residues at the N(1) position of a small subset of mRNAs: N(1) methylation takes place in tRNA T-loop-like structures of mRNAs and is only present at low stoichiometries.
Synonyms: TRM6; CGI-09; GCD10; MGC5029; Gcd10p
Tractability: Small molecule: a structure with a bound ligand is known. PROTAC: ubiquitination databases record sites on it; its protein half-life has been measured.
Gene: Protein-coding gene on chromosome 20 (5,937,228 to 5,950,558, reverse strand). Ensembl gene ENSG00000089195.
Subcellular location: Nucleus
Subcellular location (Human Protein Atlas): Nucleoplasm; Cell Junctions
Pathways (Reactome):
Metabolism of RNA: tRNA modification in the nucleus and cytosol
Gene Ontology:
Molecular function: protein binding; RNA binding
Biological process: mRNA processing; tRNA methylation
Cellular component: nucleoplasm; tRNA (m1A) methyltransferase complex; nucleus
Genetic constraint (gnomAD): Loss-of-function variants: 30 observed, 51.82 expected, observed/expected ratio (o/e) 0.58, 90% interval 0.43 to 0.79. The upper end of that interval is the gene's LOEUF score, 0.79, which puts it in group 3 of 6, group 1 being the genes least tolerant of losing a copy. Missense variants: 532 observed, 583.3 expected, observed/expected ratio (o/e) 0.91, 90% interval 0.85 to 0.98. Synonymous variants: 205 observed, 206.28 expected, observed/expected ratio (o/e) 0.99, 90% interval 0.89 to 1.12.
Homologues: Orthologues: chimpanzee TRMT6 (99% identical), macaque TRMT6 (99% identical), dog TRMT6 (93% identical), pig TRMT6 (93% identical), rabbit TRMT6 (93% identical), guinea pig TRMT6 (87% identical), rat Trmt6 (86% identical), mouse Trmt6 (85% identical), tropical clawed frog trmt6 (66% identical), zebrafish trmt6 (56% identical), Drosophila melanogaster Trmt6 (27% identical), Caenorhabditis elegans trmt-6 (24% identical).
Diseases named in the same sentence as TRMT6 in open-access papers:
TRMT6 is named in the same sentence as 24 diseases in open-access papers, as found by Europe PMC text mining. Sharing a sentence is not in itself a finding about the gene and the disease. The quoted sentences say what the papers report.
glioma (22 papers, 2017 to 2025). A benign or malignant brain and spinal cord tumor that arises from glial cells (astrocytes, oligodendrocytes, ependymal cells). "High expression of TRMT6 was closely associated with worse prognosis in different glioma clinical subtypes such as WHO-grade subtypes, IDH mutation status, and tumor recurrence status." (PMID 34631793, 2021). "Univariate and multivariate Cox regression analyses showed that TRMT6 is an independent prognostic risk factor in glioma." (PMID 34631793, 2021). "In view of TRMT6, the m1A writer was closely associated with clinical progression and poor overall survival in glioma; we further explore the prognosis value of TRMT6." (PMID 34631793, 2021). "Results showed that overexpression of TRMT6 was closely associated with worse OS in different glioma clinical subtypes such as WHO-grade subtypes, IDH mutation status, and tumor recurrence status." (PMID 34631793, 2021). "Specifically, TRMT6 has been reported to be associated with malignant progression in gliomas." (PMID 38824202, 2024). "To further explore the underlying mechanism of the oncogenic effect of TRMT6 in glioma, we further explored whether patients with different TRMT6 expression statuses had different biological behaviors." (PMID 34631793, 2021). "With respect to m1A methylation, inhibition of TRMT6 suppressed the proliferation, migration, and invasion of glioma cells." (PMID 40469294, 2025). "Nonetheless, we observed that TRMT6/61 promotes malignant transformation and progression by sustaining tRNA methylation in glioma." (PMID 40469294, 2025). "Bioinformatics screening revealed that TRMT6 is highly expressed in high-grade gliomas and is involved in regulating the cell cycle and the PI3K-AKT, TGF-β, MTORC1, NOTCH, and MYC pathways to promote glioma proliferation." (PMID 40469294, 2025). "The inhibition of TRMT6 significantly suppresses the proliferation, migration, and invasion of glioma cells." (PMID 40469294, 2025). "High expression of m1A-related regulators (m1A writer TRMT6, TRMT61A, and eraser ALKBH3) was associated with poor prognosis in several cancers, including hepatocellular carcinoma, colon cancer, glioma, breast cancer, and ovarian cancer." (PMID 38655053, 2024). "The inhibition of TRMT6, an m1A methyltransferase, impairs glioma cell proliferation, migration, and invasion." (PMID 38474421, 2024). "In glioma, glioblastoma, and hepatocellular carcinoma, overexpression of TRMT6/TRMT61A promotes proliferation and malignant transformation." (PMID 38304034, 2023). "tRNA methyltransferase 6 (TRMT6) and TRMT61A are implicated in the initiation of glioma, gastrointestinal cancer, and hepatocellular carcinoma (HCC)." (PMID 37531210, 2023). "TRMT6 also predicted poorer prognosis in glioma and promoted glioma cell proliferation, migration, and invasion by regulating cell cycle, MYC, TGF-β, PI3K-AKT, NOTCH, and MTORC1 pathways." (PMID 37612540, 2023). "Inhibition of Trmt6 resulted in decreased proliferation in glioma cell lines, establishing a potential oncogenic role for TRMT6 in regulating proliferation." (PMID 35350378, 2022). "Dysregulation of m1A regulators is closely related to glioma development and progression, and inhibition of TRMT6, a methyltransferase of m1A, inhibits glioma cell proliferation, migration, and invasion." (PMID 36437944, 2022). "Bioinformatic analysis has shown that TRMT6 potentially influences glioma progression by being involved in cell cycle regulation, and the upregulation of PI3K-AKT, TGF-beta, mTORC1, NOTCH and MYC signaling pathways and other vital processes." (PMID 36012529, 2022). "Our study showed that inhibition of TRMT6 suppressed the proliferation, migration, and invasion of glioma cells." (PMID 34631793, 2021). "Then we found that overexpression of TRMT61B, TRMT6, TRMT61A, YTHDFs, ALKBH1, and ALKBH3 was significantly associated with poor overall survival in glioma." (PMID 34631793, 2021).
glioma (continued). "To investigate the migration ability of cells after transfection with TRMT6-siRNA-3, we performed a wound healing assay and found marked suppression of cell migration in glioma cells." (PMID 34631793, 2021). "Kaplan–Meier survival curves showed that overexpression of TRMT61B, TRMT6, TRMT61A, YTHDFs, ALKBH1, and ALKBH3 was significantly associated with poor overall survival in glioma." (PMID 34631793, 2021). "Then we found that overexpression of TRMT6 was markedly related to poor clinical outcomes in glioma." (PMID 34631793, 2021). "A colony formation assay demonstrated that glioma cells treated with TRMT6 siRNA-3 generated fewer colonies than the NC group." (PMID 34631793, 2021). "In summary, our data reveal that glioma cell proliferation, migration, and invasion were markedly decreased after TRMT6 silencing." (PMID 34631793, 2021). "We found that silencing TRMT6 suppressed the proliferation, migration, and invasion of glioma cells." (PMID 34631793, 2021). "In summary, our results showed that the m1A regulators, TRMT6 in particular, play important roles in the malignant progression of glioma." (PMID 34631793, 2021). "Prior studies have shown that deletion of the TRMT6/61 complex can reduce glioma cell proliferation and increase cell death." (PMID 32934298, 2020). "The elevated expression of TRMT6 may serve as a powerful and independent biomarker for poor prognosis in glioma." (PMID 40469294, 2025). "TRMT6 regulates cell cycle distribution and increases glioma cell proliferation and death." (PMID 39006762, 2024). "Additionally, TRMT6 and TRMT61A have been implicated in glioma, gastrointestinal cancer, and hepatocellular carcinoma (HCC) development." (PMID 38408075, 2024). "The downregulation of TRMT6 was recently found to suppress glioma cell migration and invasion." (PMID 38304034, 2023). "TRMT6 plays an oncogenic role in glioblastoma cells and patients: it was shown that TRMT6 is upregulated in glioblastoma, and their knockdown via siRNA decreased glioma cells’ invasion, migration and proliferation." (PMID 36012529, 2022). "In addition, to examine the proliferation ability of glioma cells, we conducted an EdU assay, which showed that glioma cell proliferation was suppressed after the inhibition of TRMT6." (PMID 34631793, 2021). "Furthermore, we demonstrated that the depletion of TRMT6 significantly impaired glioma cell colony formation, proliferation, migration, and invasion." (PMID 34631793, 2021). "Overall, these findings showed that TRMT6 might be involved in glioma progression by regulating cell cycle, PI3K-AKT, TGF-beta, MTORC1, NOTCH, and MYC pathways." (PMID 34631793, 2021). "Silencing TRMT6 suppressed the cell proliferation, migration, and invasion in glioma." (PMID 34631793, 2021). "Results showed that TRMT6 silencing could meaningfully inhibit cell proliferation, migration, and invasion in glioma." (PMID 34631793, 2021). "Mechanistically, TRMT6 may be involved in glioma progression by regulating cell cycle, PI3K-AKT, TGF-beta, MTORC1, NOTCH, and MYC pathways." (PMID 34631793, 2021). "m1A regulators, especially TRMT6, might play an essential role in the malignant progression of glioma." (PMID 34631793, 2021). "In summary, these results confirmed that TRMT6 might be a powerful biomarker for evaluating prognosis in glioma." (PMID 34631793, 2021). "In addition to bladder cancer, TRMT6/61A is also over-expressed in liver cancer and glioma." (PMID 35923465, 2022). "However, until now, there has been only one report addressing the function of TRMT6 in glioma." (PMID 34631793, 2021). "Collectively, TRMT6 may play a key role in the prognosis of glioma." (PMID 34631793, 2021). "The wound healing experiment’s results prompted us to evaluate the invasive potential of glioma cells, so we performed a Transwell assay experiment and found that suppression of TRMT6 could decrease the invasive capability of glioma cells compared to the NC group." (PMID 34631793, 2021).
glioma (continued). "A CCK-8 assay showed that TRMT6-siRNA could suppress the growth in glioma cells." (PMID 34631793, 2021). "Together with other genes like TRMT6, DNMT1, and DNMT3B, WTAP can predict overall survival in glioma patients and is correlated with poor post-operative outcomes." (PMID 38474421, 2024). "m1A‐related proteins, including ALKBH1, TRMT6, TRMT10C, and YTHDF1, are significantly overexpressed in gliomas." (PMID 39006762, 2024). "Results revealed that TRMT2B, TRMT11, METTL8, TRMT6, and TRUB2 were upregulated in glioma, while METTL6 was downregulated." (PMID 38824202, 2024). "Moreover, their findings indicated that TRMT6 may be a potent biomarker for glioma prognosis." (PMID 37679761, 2023). "The differential analysis showed that ALKBH1, TRMT6, TRMT10C, YTHDF1, and YTHDF2 were significantly overexpressed in high-grade gliomas." (PMID 34631793, 2021). "We found that ALKBH1, TRMT6, TRMT10C, YTHDF1, and YTHDF2 were significantly overexpressed in high-grade gliomas and the expression of TRMT6 and YTHDF2 was higher in IDH wild-type patients." (PMID 34631793, 2021). "Subsequently, IHC images selected from the HPA database also proved that TRMT6, TRMT61B, and YTHDF2 were upregulated in glioma tissues." (PMID 34631793, 2021). "Furthermore, TRMT6 might be a powerful and independent biomarker for prognosis in glioma." (PMID 34631793, 2021). "In addition to METTL1, TRMT6 and TRMT61 can promote malignant transformation and progression by sustaining tRNA methylation in glioma." (PMID 40469294, 2025). "Taking all the previous results together, we found that high expression of YTHDF2 and TRMT6 is closely correlated with advanced WHO stage, IDH mutation, 1p19q non-codel, and poor clinical outcome in glioma." (PMID 34631793, 2021). "Moreover, a concomitant increase in TRMT6/TRMT61 mRNA and tRNAi (Met) expression with decreased expression of PKCα mRNA was detected in highly aggressive glioblastoma as compared with Grade 2/3 glioma." (PMID 40469294, 2025).
hepatocellular carcinoma (16 papers, 2021 to 2026). A malignant tumor that arises from hepatocytes. "The elevated expression of m1A methyltransferases (TRMT10C, TRMT6) and ribosomal RNA processing protein 8 (RRP8), along with m5C reader YBX1, demonstrate a significant association with unfavorable prognosis in hepatocellular carcinoma." (PMID 40699703, 2025). "The writer TRMT6 was reported to be significantly upregulated in hepatocellular carcinoma (HCC) tissues compared to adjacent tissues, and higher expression of TRMT6 was correlated with poor prognosis in HCC patients." (PMID 35401564, 2022). "Research indicates that TRMT6 is upregulated in hepatocellular carcinoma (HCC) tissues, and it correlates with poorer overall survival and recurrence-free survival rates." (PMID 41244907, 2025). "In bladder cancer (BLCA) and hepatocellular carcinoma (HCC), the expression of TRMT6/61A is elevated, leading to increased m1A modification on tRNAs." (PMID 38943267, 2024). "Similar to m6A and m5C, TRMT6 has been found to mediate the MYC, and also the PI3K/Akt signalling pathway in vitro, thereby downregulating m1A and affecting hepatocellular carcinoma (HCC) prognosis." (PMID 34288419, 2021). "For instance, the expression of TRMT6/TRMT61A is significantly increased in hepatocellular carcinoma tissues and increased TRMT6 and TRMT61A levels are negatively associated with patient prognosis (Wang YY." (PMID 38482382, 2024). "The study showed that the m1A methyltransferase complex (TRMT6 and TRMT61A) could increase PPARδ translation, which in turn triggers cholesterol synthesis to activate Hedgehog signaling in human hepatocellular carcinoma cell lines." (PMID 36035160, 2022). "In hepatocellular carcinoma (HCC), the methyltransferase complex formed by TRMT61A and TRMT6 is highly expressed, leading to a significant increase in the m1A methylation of tRNA, especially on tRNAAla (AGC) and tRNAGlu (CTC)." (PMID 41501031, 2026).
bladder cancer (9 papers, 2022 to 2025). "Research has indicated that increased m1A modification in bladder cancer is closely linked to the abnormal expression of TRMT6/61A, which controls the target mRNA unfolded protein response (UPR) and bladder cancer advancement through tRF-3B." (PMID 40809690, 2025). "For instance, TRMT6/61A-dependent m1A modification on tRF-3 was found to restrain RNA silencing, thereby increasing the expression of unfolded protein response genes in bladder cancer." (PMID 40045194, 2025). "Specifically, the removal of TRMT6/TRMT61A resulted in decreased mRNA levels of the conventional transcription factor UPR ATF6-associated targets, leading to a reduction in bladder cancer cell proliferation and stress resistance." (PMID 40809690, 2025). "TRMT6/61A‐mediated higher m1A modification ablated gene silencing functions of tRF‐3 s, consequently inducing unfolded protein response to maintain bladder cancer cells to survive stressful tumour microenvironment." (PMID 37850543, 2024). "However, the depletion of TRMT6/TRMT61A markedly impaired the proliferative capacity of bladder cancer cell lines." (PMID 40416872, 2025). "Studies have confirmed that TRMT6/61A is abnormal in bladder cancer cells, and silencing the expression of TRMT61A in bladder cancer cells can inhibit cell proliferation and invasion and promote cell apoptosis." (PMID 36707905, 2023). "Such UPR induced stress response is significantly dampened by TRMT6/61A knockdown in both HEK293T and T24 bladder cancer cell lines." (PMID 35444240, 2022).
glioblastoma (5 papers, 2022 to 2025). The most malignant astrocytic tumor (WHO grade IV). "In highly aggressive glioblastoma, the expression of TRMT6/TRMT61A mRNA and tRNAiMet is up-regulated, and elevated TRMT6/TRMT61A can modulate the translation of mRNAs which encode proteins serving as oncogenic factors." (PMID 40483535, 2025). "In highly aggressive glioblastoma multiforme, unlike Grade II/III glioblastomas, a significant upregulation in TRMT6/TRMT61A expression was noted." (PMID 38943267, 2024).
colon cancer (4 papers, 2021 to 2024). "Clinical significance of TRMT6 in HCC and colon cancers is very important." (PMID 33552715, 2021).
liver cancer (4 papers, 2021 to 2023). An epithelial or non-epithelial malignant neoplasm that arises from the liver. "Parallelly, DKO in MycOE mice also displayed suppression of liver cancer development compared to littermate control mice.Trmt6/Trmt61a DKO reduced levels of m1A, Pparδ, and Hmgcs2 in MycOE or DEN induced liver tumor tissues." (PMID 34728628, 2021). "Altogether, thiram acts as an efficient inhibitor against TRMT6/TRMT61A complex that effectively inhibits tumor growth of liver cancer." (PMID 34728628, 2021). "Altogether, the Trmt6/Trmt61a-m1A promotes mouse liver cancer development." (PMID 34728628, 2021). "Finally, we identify a potent inhibitor against TRMT6/TRMT61A complex that exerts effective therapeutic effect on liver cancer." (PMID 34728628, 2021). "Moreover, TRMT6 was also highly expressed in CSCs of human liver cancer tissues by immunofluorescence staining and qRT-PCR analysis." (PMID 34728628, 2021). "We found that Trmt6−/−, Trmt61a−/−, or double knockout (DKO) mice remarkably suppressed development of mouse liver cancers with DEN treatment compared to littermate control mice." (PMID 34728628, 2021). "In brief, they confirmed that TRMT6/TRMT61A increases m1A methylation in a subset of tRNAs to enhance PPAR translation, which in turn induces cholesterol production to activate Hedgehog signaling pathway, ultimately promoting self-renewal of liver cancer stem cells and HCC tumorigenesis." (PMID 37679761, 2023). "Therefore, this study took this as an entry point to speculate that TRMT6 may regulate the PI3K/AKT signaling pathway in which mTOR is located, thereby regulating the proliferation of liver cancer cells." (PMID 36707905, 2023).
breast carcinoma (3 papers, 2024 to 2025). "Notably, the expression and biological roles of tRNA m1A methyltransferase 6 noncatalytic subunit (TRMT6) in breast cancer, particularly in triple-negative breast cancer (TNBC), are unknown." (PMID 41391019, 2025).